ADAMTS10 (ADAM metallopeptidase with thrombospondin type 1 motif 10)
Description:
Metalloprotease that participate in microfibrils assembly. Microfibrils are extracellular matrix components occurring independently or along with elastin in the formation of elastic tissues.
Synonyms: ADAM-TS10; ADAMTS-10; WMS; WMS1
Tractability: Antibody: UniProt places it where antibodies can reach, with high confidence; its Gene Ontology location is reachable by antibodies, with high confidence; UniProt predicts a signal peptide or a membrane-spanning region.
Gene: Protein-coding gene on chromosome 19 (8,580,240 to 8,610,735, reverse strand). Ensembl gene ENSG00000142303.
Subcellular location: Secreted, extracellular space, extracellular matrix
Pathways (Reactome):
Disease: Defective B3GALTL causes PpS
Metabolism of proteins: O-glycosylation of TSR domain-containing proteins
Gene Ontology:
Molecular function: protein binding; metalloendopeptidase activity; metallopeptidase activity
Biological process: extracellular matrix organization; proteolysis
Cellular component: extracellular matrix
Genetic constraint (gnomAD): Loss-of-function variants: 48 observed, 130.71 expected, observed/expected ratio (o/e) 0.37, 90% interval 0.29 to 0.47. The upper end of that interval is the gene's LOEUF score, 0.47, which puts it in group 2 of 6, group 1 being the genes least tolerant of losing a copy. Missense variants: 1,129 observed, 1,537.6 expected, observed/expected ratio (o/e) 0.73, 90% interval 0.7 to 0.77. Synonymous variants: 620 observed, 644.51 expected, observed/expected ratio (o/e) 0.96, 90% interval 0.9 to 1.03.
Homologues: Orthologues: macaque ADAMTS10 (99% identical), rabbit ADAMTS10 (96% identical), pig ADAMTS10 (95% identical), guinea pig ADAMTS10 (95% identical), rat Adamts10 (94% identical), mouse Adamts10 (94% identical), dog ADAMTS10 (88% identical), chimpanzee ADAMTS10 (84% identical), tropical clawed frog adamts10 (69% identical), zebrafish adamts10 (66% identical). Paralogues in human: ADAMTS6 (60% identical), ADAMTS7 (37% identical), ADAMTS16 (37% identical), ADAMTS18 (37% identical), ADAMTS12 (35% identical), ADAMTS9 (34% identical), ADAMTS20 (32% identical), ADAMTS14 (29% identical), ADAMTS2 (28% identical), ADAMTS17 (28% identical), ADAMTS3 (28% identical), ADAMTS19 (28% identical), and 13 more.
Diseases named in the same sentence as ADAMTS10 in open-access papers:
ADAMTS10 is named in the same sentence as 49 diseases in open-access papers, as found by Europe PMC text mining. Sharing a sentence is not in itself a finding about the gene and the disease. The quoted sentences say what the papers report.
Weill-Marchesani syndrome (18 papers, 2005 to 2024). Weill-Marchesani syndrome (WMS) is a rare condition characterized by short stature, brachydactyly, joint stiffness, and characteristic eye abnormalities including microspherophakia, ectopia of the lens, severe myopia, and glaucoma. "Consistently, in humans, ADAMTS10, whose mutation causes Weill-Marchesani syndrome characterized by short stature and thickened skin, increases TGF-β activation in a dose-dependent manner." (PMID 38980840, 2024). "Recessive ADAMTS10 mutations lead to an acromelic dysplasia, Weill-Marchesani syndrome 1 (WMS1), whereas dominant FBN1 mutations cause a phenotypically similar disorder, WMS2, suggesting a functional relationship between ADAMTS10 and fibrillin-1." (PMID 35503090, 2022). "One gene (ADAMTS10) was overlapping with an identified signal for height (index variant rs62621197) and it is involved in Weill-Marchesani syndrome (MIM: 277600), a connective tissue disorder characterized by short stature." (PMID 28552196, 2017). "ADAMTS10 mutations cause Weill-Marchesani syndrome (WMS), implicating it in fibrillin microfibril biology since some fibrillin-1 mutations also cause WMS." (PMID 27779234, 2016). "In addition to glaucoma, autosomal recessive mutations in ADAMTS10 cause Weill-Marchesani Syndrome (WMS), a rare connective tissue disorder characterized by short stature and ocular abnormalities including glaucoma." (PMID 36148008, 2022). "ADAMTS10 has been characterized as a metalloproteinase involved in fibrillin-rich microfibril biogenesis, and its mutations have been implicated in the connective tissue disorder Weill-Marchesani syndrome." (PMID 30287421, 2018). "Similarly, rs62621197 (WEAF 4.2%, beta = −0.139, p = 3.22 × 10−69) resides in ADAMTS10, null mutations in which are implicated in Weill-Marchesani syndrome, characterized by short stature." (PMID 28552196, 2017). "Recently, an autosomal recessive form of Weill-Marchesani syndrome (WMS) has been attributed to null mutations of the ADAMTS10 gene." (PMID 15693998, 2005). "Mutations in human ADAMTS10 and ADAMTS17 cause Weill-Marchesani syndrome, which is characterized by short stature and eye abnormalities including microspherophakia (the lens of the eye is smaller than normal and spherically shaped)." (PMID 26994289, 2016). "Mutations in ADAMTS10, ADAMTS17 and in fibrillin 1 (FBN1) have been associated with a Weill-Marchesani syndrome (WMS) (OMIM 277600)." (PMID 25372548, 2014). "Studies of Weill-Marchesani syndrome strongly suggest ADAMTS10 (GeneID: 81794) regulates TGF βsignaling through its interactions with the ECM component, fibrillin-1 (GeneID: 2200)." (PMID 18454205, 2008). "ADAMTS10 promotes fibrillin-1 microfibril assembly, consistent with the observation that recessive ADAMTS10 mutations and dominantly inherited FBN1 mutations each lead to Weill-Marchesani syndrome." (PMID 35503090, 2022). "In addition, four individuals (one affected) have an exonic heterozygous deletion not found in controls in ADAM metallopeptidase with thrombospondin type 1 motif (ADAMTS10), a candidate gene for Weill-Marchesani syndrome." (PMID 25887117, 2015). "ADAMTS10 and ADAMTS17 mutations give rise to Weill-Marchesani syndrome (WMS)-like spectrum and have been functionally associated with the assembly of fibrillin microfibrils." (PMID 33352066, 2020).
glaucoma (17 papers, 2012 to 2025). Increased pressure in the eyeball due to obstruction of the outflow of aqueous humor. "We suspect that the softer ADAMTS10-mutant sclera is in part responsible for an improved IOP tolerance with slower progression of ONH atrophy and vision loss in Beagles with ADAMTS10-OAG compared to other glaucoma-affected canine breeds with comparable IOPs." (PMID 38130820, 2023). "Previously, we identified a G661R mutation in ADAMTS10 as disease-causative for a colony of Beagle dogs with autosomal recessive inheritance of glaucoma." (PMID 36148008, 2022). "Mutations in ADAMTS10 and in ADAMTS17, which is genetically and functionally highly similar to ADAMTS10 cause glaucoma in dogs." (PMID 36148008, 2022). "Our study suggests that ADAMTS10 is another example of an ocular developmental gene that plays a role in glaucoma pathogenesis and suggests that the glaucoma-causative G661R mutation interferes with this developmental role." (PMID 36148008, 2022). "Since dogs with the glaucoma-causing ADAMTS10 mutations have elevated IOP, we anticipated that mice with microfibril deficiencies would as well." (PMID 30406200, 2018). "Previously, we identified a mutation in a microfibril-associated gene ADAMTS10, as causative for primary open angle glaucoma in a colony of dogs." (PMID 30406200, 2018). "This study aims to investigate how age affects scleral biomechanical properties in a canine glaucoma model with ADAMTS10 mutation, whose extracellular matrix is concomitantly influenced by the mutation and an increased mechanical load from an early age." (PMID 27271467, 2016). "The role of the ADAMTS family members in glaucoma pathogenesis is further highlighted by the identification of a mutation in ADAMTS10 as the cause of glaucoma in the Beagle and Norwegian Elkhound dog breeds." (PMID 26683476, 2015). "Mutations in ADAMTS10 (CFA20) have previously been associated with primary open angle glaucoma (POAG) in the Beagle and Norwegian Elkhound." (PMID 26474315, 2015). "The associated region contains a previously identified glaucoma gene, ADAMTS10, which was subjected to mutation screening in the coding regions." (PMID 25372548, 2014). "The aim of the present study was to assess the potential associations of polymorphisms in the candidate genes SRBD1, ELOVL5, and ADAMTS10, with the development of canine glaucoma." (PMID 24040232, 2013). "In addition, knock-in of an ADAMTS10 mutation that causes glaucoma in dogs into the mouse Adamts10 locus also resulted in short stature." (PMID 41034152, 2025). "Although we did not address BMP signaling since our focus was on TGFβ due to its importance in glaucoma, the effects of ADAMTS10 deficiency could vary between tissues, developmental stages and species investigated." (PMID 36148008, 2022). "Although mutations in ADAMTS10 have long been known to cause autosomal recessive Weill-Marchesani Syndrome which is characterized by short stature and ocular abnormalities, more recent work has shown that certain mutations in ADAMTS10 cause glaucoma in dogs." (PMID 36148008, 2022). "However, ADAMTS10 may be still a candidate gene for glaucoma in dogs, including Shiba-Inu and Shih-Tzu, because other ADAMTS10 variants have yet to be investigated for their association with canine glaucoma." (PMID 24040232, 2013). "Our OPA data supported this: differences between ADAMTS10-mutant and normal dogs became less significant when excluding young dogs before the development of glaucoma." (PMID 38130820, 2023). "This study shows a significantly smaller OPA in ADAMTS10-mutants whose sclera is softer than the normal, supporting the potential clinical value of OPA as a measure of glaucoma susceptibility." (PMID 38130820, 2023). "For example, Beagles with ADAMTS10-OAG tolerate elevated IOP much better, with slower progression of vision loss, than other glaucoma-affected breeds with comparable IOPs." (PMID 38130820, 2023).
glaucoma (continued). "We took advantage of a well-defined, clinically relevant canine glaucoma model, the OAG-affected Beagle, with a G661R missense mutation in the ADAMTS10 gene." (PMID 38130820, 2023). "A developmental role for ADAMTS10 is suggested by its association with WMS, a dysmorphic connective tissue disorder characterized by short stature and ocular phenotypes, including glaucoma." (PMID 36148008, 2022). "Several of the differentially expressed genes have previously been reported to be associated with elevated IOP and/or glaucoma, including MYOC, ADAMTS10, LTBP2, LOXL1, TGFBR3, CYP1B1, and EFEMP15,28,43–45." (PMID 34385434, 2021). "This is of interest, as the canine model of spontaneous primary open angle glaucoma (POAG beagle), is associated with a mutation in the metalloproteinase ADAMTS10, which has a cDNA of 3312 bases, too large to be accommodated by scAAV vectors." (PMID 26052939, 2015). "In man, homozygous mutations in ADAMTSL4, ADAMTS10, ADAMTS17 cause various ocular phenotypes including ectopia lentis, myopia and glaucoma." (PMID 26474315, 2015). "This study establishes also a new spontaneous canine model for glaucoma research to study the ADAMTS10 biology in optical neuropathy." (PMID 25372548, 2014). "Our affected dogs establish a new model to study ADAMTS10 biology in the microfibrillin theory of the glaucoma." (PMID 25372548, 2014). "In this study, we investigated the association between polymorphisms of the glaucoma candidate genes, SRBD1, ELOVL5, and ADAMTS10, and glaucoma in Shiba-Inus and Shih-Tzus." (PMID 24040232, 2013). "In this study, to verify recent genetic findings, we investigated the association between glaucoma in Shiba-Inu and Shih-Tzu dogs and polymorphisms of glaucoma candidate genes, SRBD1, ELOVL5 and ADAMTS10, using direct sequencing." (PMID 24040232, 2013). "In dogs, mutations in ADAMTS10 and ADAMTS17 were associated with primary open angle glaucoma." (PMID 41034152, 2025). "DNA testing revealed that the dog did not carry the Gly661Arg ADAMTS10 mutation responsible for primary open angle glaucoma (POAG) in Beagles." (PMID 30832652, 2019). "Furthermore, the protein product of ADAMTS10 (ADAM metallopeptidase with thrombospondin type 1 motif, 10), which has been identified as causative of glaucoma in a canine model of the disease, is involved in ECM formation." (PMID 22312193, 2012). "ADAMTS10 and ADAMTS17 both contribute to formation and function of fibrillin-1 microfibrils, leading us to form the hypothesis that microfibril defects can cause glaucoma." (PMID 30406200, 2018). "Therefore, it is necessary to perform a comprehensive genetic analysis of the region and clarify whether ADAMTS10 is a candidate gene for glaucoma not only in Beagles, but also in other breeds." (PMID 24040232, 2013). "Involvement of ADAMTS10 with glaucoma has been verified in another dog breed and extended to include ADAMTS17 which is structurally and functionally highly similar to ADAMTS10." (PMID 36148008, 2022). "As genetic testing for the mutation in the ADAMTS10 and ADAMTS17 genes was not performed, the possibility of primary open-angle glaucoma in some of these cases cannot be excluded." (PMID 38444777, 2024). "In addition, we identified several transcriptional targets of GLIS1 in TM cells that previously have been implicated in TM-related functions, IOP homeostasis, and ocular hypertension/glaucoma, including MYOC, ADAMTS10, LTBP2, LOXL1, TGFBR3, CYP1B1, and EFEMP15,28,43,44." (PMID 34385434, 2021).
primary open angle glaucoma (9 papers, 2014 to 2024). "Mutations in the ADAMTS10 gene, located on chromosome 20, causes primary open angle glaucoma (POAG) in the Beagle and Norwegian Elkhound." (PMID 26401331, 2015). "Thirteen purpose-bred adult Beagles were included in this study, both normal controls (n = 4) and ADAMTS10 mutants with open-angle glaucoma (OAG; n = 9)." (PMID 34847929, 2021). "The purpose of this study was to determine a possible relationship between the G661R missense mutation in the ADAMTS10 gene and the ocular pulse amplitude (OPA), the difference between diastolic and systolic intraocular pressure (IOP), in a well-established canine model of open-angle glaucoma (OAG)." (PMID 38130820, 2023).
ectopia lentis (8 papers, 2016 to 2024). "Mutations in ADAMTS10 and ADAMTS17 phenocopy mutations in ADAMTSL4 (ectopia lentis) and ADAMTSL2 (acromelic dysplasias), suggesting common functional pathways, and ADAMTSL3 also binds directly to ADAMTS10." (PMID 38324186, 2024). "Ectopia lentis is also caused by variants in FBN1, ADAMTS10, ADAMTS17 and LTBP2, suggesting a functional relationship in the regulation of zonule assembly." (PMID 38324186, 2024). "Mutations in ADAMTSL4 cause ectopia lentis (lens dislocation), which is a key feature of WMS, and the protein composition of the ciliary zonule was altered in ADAMTS10-deficienct eyes." (PMID 32290605, 2020). "Expression of ADAMTS10 in the eye is relevant for the characteristic ectopia lentis phenotype observed in individuals with Weill–Marchesani syndrome (WMS)." (PMID 32290605, 2020). "All the genes associated with ectopia lentis phenotypes to date, (ADAMTSL4, FBN1, LTBP2, ADAMTS10, ADAMTS17) included in the clinical exome employed, revealed several genetic variants in these genes." (PMID 29751740, 2018). "Since WMS patients present with ectopia lentis and other eye disorders, the distribution of ADAMTS10 in the eye was analysed." (PMID 30060141, 2018). "Whereas mice lacking or mutant for Adamts10 have not been reported to develop WMS1-like lens defects including microspherophakia, ectopia lentis, and cataract, homozygous Em/J mice developed cataract with full penetrance—suggesting that Adamts10 is a marginal candidate gene for Em." (PMID 36891866, 2023). "Autosomal recessive Weill–Marchesani (OMIM # 613195)—clinical features in this form can overlap autosomal-dominant Weill–Marchesani syndrome, but genes involved in the condition are: ADAMTS10, ADAMTS17, and LTBP2 (described in one family, without Ectopia Lentis)." (PMID 37443678, 2023).
acromelic dysplasia (4 papers, 2020 to 2024). "ADAMTS10, ADAMTS17 and, ADAMTSL2 are also involved in the pathogenic mechanism of acromelic dysplasia." (PMID 34912367, 2021).
gastric cancer (3 papers, 2022 to 2024). A primary or metastatic malignant neoplasm involving the stomach. "ADAMTS10 was reported to alter the JAK/STAT/c-MYC pathway and reprogram macrophages in gastric cancer, possibly inhibiting cancer progression, and was shown to be a plausible prognostic biomarker." (PMID 39329961, 2024).
buphthalmia (2 papers, 2016 to 2023). "Axial length was significantly larger in our mutant vs. normal dogs, with a significant positive correlation between IOP and AXL, consistent with the chronic IOP increase associated with ADAMTS10-OAG and the development of buphthalmos." (PMID 38130820, 2023).
Primary glaucoma (2 papers, 2014 to 2015). "Finally, mutations in closely related genes, ADAMTS10 and ADAMTSL4, are known to be involved in primary glaucoma and other ocular connective tissue disorders in both man and dog." (PMID 26474315, 2015).
Ataxia (1 paper, 2023). Ataxia refers to impaired coordination of voluntary muscle movement. "Both the human counterparts of Adamts10 and Abhd12 are clinically associated with syndromic forms of cataract known as Weil-Marchesani syndrome 1 and polyneuropathy, hearing loss, ataxia, retinitis pigmentosa, and cataract syndrome, respectively." (PMID 36891866, 2023).
breast carcinoma (1 paper, 2022). "ADAMTS10 is a member of the disintegrin-like and metalloprotease with thrombospondin type I motif family proteins that are implicated in breast cancer development and progression." (PMID 35886011, 2022). "Together with ADAMTS3, ADAMTS10 expression appeared reduced in breast cancer tissues." (PMID 35886011, 2022).
carpal tunnel syndrome (1 paper, 2020). Entrapment of the median nerve in the wrist that is characterized by numbness, tingling and painful movement. "ADAMTS10 and ADAMTS17 were identified in a genome-wide association study (GWAS) of more than 12,000 cases versus 390,000 controls as susceptibility loci likely to cause carpal tunnel syndrome." (PMID 32290605, 2020). "However, the possibility of studying double knockout mice for ADAMTS10 and ADAMTS17 may provide an opportunity to gain some insights into the contribution of these protease to multigenic traits, such as carpal tunnel syndrome or body fat distribution." (PMID 32290605, 2020).
clear cell renal carcinoma (1 paper, 2024). A malignant epithelial neoplasm of the kidney characterized by the presence of lipid-containing clear cells within a vascular network. "In clear cell renal carcinoma, ADAMTS10 was upregulated, and its inhibition resulted in the impaired ability of cells to proliferate, invade, and migrate." (PMID 39329961, 2024).
colorectal cancer (1 paper, 2024). A primary or metastatic malignant neoplasm that affects the colon or rectum. "In this study, we aimed to evaluate the expression of SEMA7A, SEMA4D, ADAM8, and ADAMTS10 in colorectal cancer (CRC) in relation to the mutational landscape of KRAS, NRAS, BRAF, PIK3CA, and AKT genes, microsatellite instability (MSI) status, and clinicopathological features." (PMID 39329961, 2024).
disc degeneration (1 paper, 2020). "Both of them are involved in the process of disc degeneration, with MMP-3 up-regulated and ADAMTS-10 down-regulated in degenerative intervertebral disc tissue." (PMID 32210816, 2020).
hypertrophic obstructive cardiomyopathy (1 paper, 2023). "Of six patients with truncating mutations in the catalytic domain of ADAMTS10, two had pulmonary stenosis, and two had aortic and pulmonary stenosis with dysplastic valves and hypertrophic obstructive cardiomyopathy." (PMID 37240210, 2023).
lumbar disc degeneration (1 paper, 2024). "Conversely, the individual injections of MMP1a and ADAMTS10 led to discernible lumbar disc degeneration but did not impact the expression levels of other members of the MMP and ADAMTS families." (PMID 38877576, 2024).